AQP1 (aquaporin 1 (Colton blood group))
Diseases named in the same sentence as AQP1 in open-access papers (continued):
Sharing a sentence is not in itself a finding about the gene and the disease.
cardiac hypertrophy (8 papers, 2018 to 2024). "Here AQP1 might be important because Aqp1 knockout causes cardiac hypertrophy in mice." (PMID 29449936, 2018). "Previously, AqB011-treated mice were used to assess the role of AQP1 in cardiac hypertrophy, and 5-PMFC was used at doses up to 2.5 mM in human red blood cells and rodent models of sickle cell disease for anti-sickling effects." (PMID 37760476, 2023). "AQP1 is essential for water homeostasis and vascular health and studies in AQP1-KO mice showed that these animals suffer from cardiac hypertrophy." (PMID 33673336, 2021). "The finding that bacopasides block AQP1 has been successfully translated into a novel treatment in vivo, with recent work showing that cardiac hypertrophy induced by AQP1-mediated fluxes of hydrogen peroxide H2O2 was prevented by systemic treatment with bacopaside II." (PMID 34769339, 2021). "Given that the duration of an environmental challenge was unlikely to cause profound cardiac hypertrophy and the large increase in heart weight, we measured tissue water content and relative protein abundance of aquaporin 1 (AQP1), which is frequently associated with edema." (PMID 39212770, 2024). "The clinically approved AQP1 inhibitor, Bacopaside II, a triterpene saponin natural compound, impaired AQP1-mediated H2O2 permeability in mice and human myocytes, attenuating cardiac hypertrophy in a murine model." (PMID 39125952, 2024).
cervical carcinoma (8 papers, 2014 to 2025). A carcinoma arising from either the exocervical squamous epithelium or the endocervical glandular epithelium. "The decreased expression correlated AQP1 with progressive symptoms characteristic of cervical cancer." (PMID 33271827, 2020). "Our results indicate that AQP1 and AQP3 are closely associated with tumor vascularization, the progression, invasion and metastasis of cervical carcinoma." (PMID 24918928, 2014). "Using this signature, the patients were divided into Cluster A and Cluster B. Compared with Cluster A, most cuproptosis genes (such as CCDC22, PDHA1, ARF1, and AQP1) in Cluster B were highly expressed, resulting in a better prognosis for patients with cervical cancer." (PMID 41142609, 2025). "The HPV infection status and the overexpression of AQP1 and 3 are associated with poor outcome of cervical cancer; however, their overexpression levels are not independent risk factors which are related with the prognosis of cervical carcinoma." (PMID 33796134, 2021). "AQP1 was localized in the tumor vessels, while AQP3 showed increased expression in cervical cancer, compared to intraepithelial neoplasia, and normal cells." (PMID 33271827, 2020). "We also analyzed the correlation between AQP1 and AQP3 expression and prognosis in cervical carcinoma." (PMID 24918928, 2014). "Immunofluorescent and immunohistochemical assays were performed to determine the localization and expression of AQP1 and AQP3 in cervicitis, early stage and advanced stage cervical carcinoma." (PMID 24918928, 2014). "One-way ANOVA, the Χ2 test and rank correlation analysis demonstrated that positive expression rates of AQP1 and AQP3 were significantly related to clinical stage, tumor diameter, lymphatic metastasis and the tumor infiltration depth in cervical carcinoma." (PMID 24918928, 2014). "We observed that AQP1 and AQP3 exhibited different expression patterns in cervical carcinoma, CIN and normal tissues at both the mRNA and protein levels." (PMID 24918928, 2014). "The differences in AQP1 and AQP3 mRNA expression between mild cervicitis, early stage and advanced stage cervical carcinoma were significant (P<0.05)." (PMID 24918928, 2014). "Expression of AQP1 and AQP3 were remarkably upregulated in cervical carcinoma tissues compared to CIN and mild cervicitis." (PMID 24918928, 2014). "AQP1 and AQP3 were expressed in mild cervicitis, early stage and advanced stage cervical carcinoma." (PMID 24918928, 2014). "AQP1 was predominantly localized to the microvascular endothelial cells in the stroma of mild cervicitis, CIN 2-3 and cervical carcinoma, and the expression of AQP1 was significantly higher in cervical carcinoma than CIN2-3 and mild cervicitis." (PMID 24918928, 2014). "Tumor infiltration depth, treatment protocol, HPV infection status, serum SCC-Ag level, and AQP1 and AQP3 expression were not independent risk factors in cervical carcinoma." (PMID 24918928, 2014). "AQP1 and AQP3 mRNA expression increased from mild cervicitis to cervical carcinoma." (PMID 24918928, 2014). "In this study, we investigated the different expression of AQP1andAQP3 in both transcription and translation level in the cervical lesions of women of Uygur ethnicity from Xinjiang, China, and analyzed the prognostic value of AQP1 and AQP3 in cervical carcinoma." (PMID 24918928, 2014). "Upregulation of AQP1 and AQP3 may facilitate progression, invasion and metastasis in cervical carcinoma, suggesting that AQPs may represent potential targets for the treatment of cervical carcinoma in the future." (PMID 24918928, 2014).
malignant mesothelioma (8 papers, 2014 to 2024). A malignant neoplasm of the pleura or peritoneum, arising from mesothelial cells. "The major allele of rs1049305, located in the 3’-untranslated region of the AQP1 gene, was reported to be a risk SNP for malignant mesothelioma, and the minor allele of rs1049305 was associated with water retention in cirrhotic patients and running performance in marathons." (PMID 38021552, 2023). "Inhibition of AQP1 by AqB050 or siRNA knockdown resulted in a decreased cell growth in primary malignant mesothelioma cells obtained from pleural effusions." (PMID 38336645, 2024). "We have reported previously that AQP1 expression by MM tumour cells is an independent prognostic factor for improved survival times in malignant mesothelioma: higher levels of AQP1 expression by tumour cells only (i.e., not vascular cells) predict improved survival." (PMID 25821338, 2015).
asthma (7 papers, 2014 to 2025). "Upon analyzing sputum samples from 34 patients with mild to moderate asthma, a positive correlation was observed between AQP1 and AQP5 levels." (PMID 39440058, 2024). "Researchers established a mouse model of asthma and concluded that Angelicae Sinensis Radix can promote the expression of AQP1 and its gene in lung tissue, thereby exerting a certain therapeutic effect on Yin deficiency asthma." (PMID 36532729, 2022). "Another study on ovalbumin-induced asthma models also reported reduced mRNA levels for AQP1, AQP4, and AQP5 but elevated AQP3 mRNA levels." (PMID 30397774, 2019). "Asthma models based on ovalbumin instillation exhibit changes in expression levels of AQP1, AQP3, AQP4, and AQP5." (PMID 30397774, 2019). "In a recent study, increases in AQP1 and AQP5 content in the sputum were proposed as possible diagnostic markers for mild asthma." (PMID 30397774, 2019). "Recently, a mouse model of asthma induced by ovalbumin has been used to study the mRNA and protein expression of AQP1 and AQP5." (PMID 24917931, 2014). "Previous studies also showed that AQP1 and AQP5 levels were significantly reduced in OVA‐induced mouse asthma models, which induced increased alveolar fluid viscosity and mucus plug formation." (PMID 41280738, 2025). "AQP-1 plays a role in fluid flux and eosinophil movement, whereas AQP-5 is involved in pulmonary hyper-responsiveness and airway inflammation in asthma." (PMID 38203236, 2023). "Among the various lung injuries investigated, there was a reduction in AQP1 expression or activity, and AQP1 and AQP4 mRNA expression was downregulated in allergen-induced mouse models of asthma." (PMID 25009607, 2014). "Hence, our hypothesis posits that both AQP1 and AQP5 could serve as potential markers for asthma." (PMID 39440058, 2024). "The authors found that both AQPs were significantly increased by treatment with dexamethasone, ambroxol, and terbutaline, indicating that AQP1 and AQP5 are closely related to pulmonary edema but not to eosinophil infiltration or mucus secretion in patients with asthma." (PMID 24917931, 2014).
mesothelioma (7 papers, 2015 to 2024). A usually malignant and aggressive neoplasm of the mesothelium which is often associated with exposure to asbestos. "By contrast, AQP1 high expression in mesotheliomas is associated with improved survival rates, as elsewhere by us reported." (PMID 33807998, 2021). "Concerning mesothelioma subtypes, the authors showed that the AQP1 staining pattern decreases as the survival period of these patients decreases: sarcomatoid < biphasic < epithelioid." (PMID 35741021, 2022). "The specific blockade of AQP1 in mesothelioma using a pharmacological blocker (AqB050) or using a specific AQP1-siRNA decreased cell proliferation, motility, and metastatic potential in vitro but not in vivo." (PMID 35741021, 2022). "Aquaporin ion channels have roles in bulla mucosa physiology, and AQP1 in particular has a role in mesothelioma cell adhesion, interaction with ECM and cell migration." (PMID 30898767, 2019).
neuroblastoma (7 papers, 2016 to 2023). Neuroblastoma (NB) is the most common solid, extracranial childhood tumor. "We have identified further hypoxia-associated prognostic factors for neuroblastoma including CXCR4, PGK1 and AQP1 leading to increased metastases." (PMID 35328549, 2022). "In this study, we investigate the relationship of AQP1 expression with other adverse factors in neuroblastoma." (PMID 33467498, 2021). "Although we have previously observed that AQP1 expression leads to an increased migratory behavior of neuroblastoma cells through its up-regulation under hypoxic conditions, we observe here that hypoxia leads to a reduction of NMYC in the same cells." (PMID 33467498, 2021). "Neuroblastoma cells with a high AQP1 expression show a distinct enhanced migratory pattern compared to cells with low AQP1 expression." (PMID 33644043, 2021). "Our data suggest that expression of AQP1 is linked to HIF-1α as well as HIF-2α and that this hypoxia-related profile is linked to migratory processes in neuroblastoma." (PMID 33644043, 2021). "We find that AQP1 expression in neuroblastoma cells is up-regulated by hypoxic conditions, and that increased AQP1 expression enabled the cells to form a phenotype which is associated with migratory properties and increased cell agility." (PMID 33644043, 2021). "AQP1 expression of neuroblastoma cell was evaluated by immunohistochemistry, quantitative PCR and western blotting under normoxic and hypoxic conditions." (PMID 33644043, 2021). "Our results show that while AQP1 expression leads to an increased migratory behavior of neuroblastoma cells under hypoxic conditions, we find that hypoxia is associated with a reduction of NMYC in the same cells." (PMID 33467498, 2021). "We have previously shown that AQP1 expression leads to an increased migratory behavior of neuroblastoma cells through its up-regulation under hypoxic conditions (Huo, to be published)." (PMID 33467498, 2021). "AQP1 and HIF-1α have also been associated with invasiveness and migration in neuroblastoma and other cancers as well as with resistance to chemotherapy." (PMID 33644043, 2021). "Our experiments show that AQP1 changes in the modified tumor cells are functional and lead to an enhanced or decreased water transport of neuroblastoma cells." (PMID 33644043, 2021). "In order to compare functional properties of neuroblastoma cells that express different levels of AQP1, knock-down and over-expressing SH-SY5Y cells were constructed." (PMID 33644043, 2021). "In this study, we investigate to what extent the expression of AQP1 in neuroblastoma correlates with or is dependent on changing cellular factors such as differentiation, expression of know adverse factors such as NMYC and NCAM, and metastatic spread related to CXCR4." (PMID 33467498, 2021). "AQP1 expression in neuroblastoma cells is up-regulated by hypoxic conditions." (PMID 33644043, 2021). "We show that AQP1 expression is up-regulated by hypoxia in neuroblastoma." (PMID 33644043, 2021). "In this context it could be important to further investigate the role of AQP1 expression in neuroblastoma cancer stem cells, which might serve as an anti-tumor target." (PMID 33644043, 2021). "The objectives of this study have been to determine whether AQP1 expression in neuroblastoma is dependent on hypoxia, to demonstrate whether AQP1 is functionally relevant for migration, and to further define AQP1-dependent properties of the migrating cells." (PMID 33644043, 2021). "In this study, we investigate to what extent the expression of AQP1 in neuroblastoma correlates with changing cellular factors such as the hypoxic status, differentiation, expression of known adverse factors such as NMYC and NCAM, and CXCR4-related metastatic spread." (PMID 33467498, 2021). "This goes hand in hand with a greater potential of AQP1-positive cells to migrate in neuroblastoma." (PMID 33671521, 2021).
neuroblastoma (continued). "Our own investigations in migrating neuroblastoma cells have revealed an increased expression of the water channel AQP1 that furthers migration by promoting water in- and efflux through the tumor cell membrane and facilitating restructuring of the cytoskeleton." (PMID 34065626, 2021). "The objectives of this study were to determine whether AQP1 expression in neuroblastoma is dependent on hypoxia, to demonstrate whether AQP1 is functionally relevant for migration, and to further define AQP1-dependent properties of the migrating cells." (PMID 33644043, 2021). "Together with an increased AQP1 expression in migrated tumor cells, we observe an increase of HIF-1α and HIF-2α in the migrated neuroblastoma cells." (PMID 33644043, 2021). "Moreover, hypoxia can significantly increase known adverse factors in neuroblastoma such as NMYC, CXCR4, PGK1 and AQP1, amongst others, leading to tumor progression and increased metastases." (PMID 35328549, 2022). "AQP1 expression correlates with a hypoxic profile of these cells with increased HIF-1α and HIF-2α expression, as well as with NMYC and NCAM expression in two out of three neuroblastoma cell lines." (PMID 33467498, 2021). "This AQP1 expression correlates with a hypoxic profile of these cells with increased HIF-1α and HIF-2α expression, as well as with NMYC and NCAM expression in two out of three neuroblastoma cell lines." (PMID 33467498, 2021). "Established and experimental adverse prognostic factors of neuroblastoma include amplification of NMYC, expression of the chemokine receptor CXCR4 that is responsible for metastatic homing and the hypoxia-dependent water channel aquaporin 1 (AQP1)." (PMID 33671521, 2021). "The presence of AQP1 and its impact on tumor progression and clinical impact in neuroblastoma has not been addressed." (PMID 33644043, 2021). "AQP1 and not CXCR4 is the initiator of migration in neuroblastoma." (PMID 33467498, 2021).
osteoarthritis (7 papers, 2019 to 2024). A noninflammatory degenerative joint disease occurring chiefly in older persons, characterized by degeneration of the articular cartilage, hypertrophy of bone at the margins and changes in the synovial membrane. "In studies investigating the pathogenesis of osteoarthritis, researchers found that the expression of AQP1 is positively correlated with caspase-3." (PMID 38334883, 2024). "The mRNA and protein expression of AQP1, -3 and -4 were significantly decreased in fibrocartilage compared to hyaline cartilage and in articular cartilage from older osteoarthritis patients compared to that from young patients." (PMID 34650163, 2021).
renal cell carcinoma (7 papers, 2014 to 2023). "Moreover, evaluating AQP1 concentrations in the urine of patients suffering renal cell carcinoma has shown to be a helpful biomarker." (PMID 36233821, 2022). "Furthermore, measuring AQP1 levels in the urine has proven to be a useful biomarker for renal cell carcinoma." (PMID 30555637, 2018). "Subjects with known renal cell carcinoma have a 12-fold increase in urine AQP1 concentration." (PMID 30555637, 2018). "In Renal Cell Carcinoma (RCC), AQP1 expression is generally low, and its association with overall survival (OS) has been well-established." (PMID 37904849, 2023). "Immunohistochemical analysis with a panel of kidney-specific markers (AQP1, PAX2, and CK7) demonstrated that these tumors were renal cell carcinomas." (PMID 26418749, 2015). "The eleven patients with positive AQP1 signals were determined to have clear cell renal cell carcinoma (n = 5), papillary renal cell carcinoma (n = 4), chromophobe RCC (n = 1), oncocytoma (n = 1), cystic nephroma (n = 1), and unclassified RCC (n = 1)." (PMID 24803718, 2014).
renal fibrosis (7 papers, 2019 to 2025). A final common manifestation of a wide variety of chronic kidney diseases characterized by glomerulosclerosis and tubulointerstitial fibrosis. "Previous studies demonstrate that decreased expression of OAT1 is linked to accelerated oxidative stress and inflammation, and loss of ATPase and AQP1 in TECs are associated with renal fibrosis." (PMID 37029114, 2023). "Masson staining was performed and found that overexpression of AQP1 attenuated renal fibrosis in septic AKI rats." (PMID 39238634, 2024). "In renal fibrosis, inhibiting EMT can ameliorate the loss of AQP1, indicating that AQP1 is involved in the EMT process." (PMID 35068345, 2022). "Obviously, 4-PBA cotreatment indeed inhibited the activation of ER stress and also prevented BV-induced E- to N-cadherin switch and the proteins involved in pro-EMT or renal fibrosis, while restoring the expressions of AQP1, ATP1A1, and SLC22A6 in human renal tubule epithelia." (PMID 35873571, 2022). "Small PAR‐1‐dependent changes in EMT, which do not change overall AQP‐1 and ZO‐1 levels, and which are not easily detected immunohistochemically, may consequently affect fibroblast accumulation and subsequent renal fibrosis." (PMID 30485646, 2019).
rheumatoid arthritis (7 papers, 2014 to 2022). A chronic, systemic autoimmune disorder characterized by inflammation in the synovial membranes and articular surfaces. "Interestingly in joint diseases associated with inflammation, it has been shown that Aqp-1 is upregulated in synoviocytes from patients with rheumatoid arthritis and fibrochondrocytes from osteoarthritic joints." (PMID 24936787, 2014). "Recent research found that the up-regulated AQP1 in synovium and cartilage of rheumatoid arthritis patients was involved in joint swelling and synovial inflammation." (PMID 31404098, 2019). "And this effect was via inhibiting NF-κB activation, suggesting AQP1 might be of potential target in rheumatoid arthritis treatment." (PMID 31404098, 2019). "Inhibition of AQP1 by acetazolamide showed a powerful therapeutic effect on rheumatoid arthritis." (PMID 31404098, 2019). "Immunohistochemistry revealed increased AQP1 expression in the articular joints of patients with rheumatoid arthritis, suggesting a potential role for synovial AQP1 in joint swelling, vasogenic synovial fluid formation, and hydrarthrosis associated with synovial inflammation." (PMID 26703073, 2015).